ARG2 (arginase 2)
Diseases named in the same sentence as ARG2 in open-access papers (continued):
Sharing a sentence is not in itself a finding about the gene and the disease.
Nasal polyposis (1 paper, 2019). Polypoidal masses arising mainly from the mucous membranes of the nose and paranasal sinuses. "Increased ARG2 expression was found in patients with CRS without nasal polyposis (FR 3.14 ± 1.16 vs. 1.31 ± 0.21, p = 0.0175), in non-allergic CRS (FR 2.55 ± 0.52 vs. 1.31 ± 0.21, p = 0.005), and non-asthmatic CRS (FR 2.42 ± 0.57 vs. 1.31 ± 0.21, p = 0.028)." (PMID 31683763, 2019).
optic neuritis (1 paper, 2021). Optic neuritis is inflammation of the optic nerve, the nerve that carries the visual signal from the eye to the brain.The conditionmay cause sudden, reduced vision in the affected eye(s). "The present study highlights the impact of arginase 2 deficiency in reducing cellular infiltrates, attenuating the activation of microglia and macrophages, mitigating axonal and myelin damage, and reducing astrogliosis in an experimental model of optic neuritis." (PMID 33735314, 2021). "Therefore, arginase 2 deficiency or blockade may positively contribute towards targeted neuroprotection in MS-induced optic neuritis." (PMID 33735314, 2021). "In conclusion, our findings demonstrate a critical involvement of arginase 2 in mediating neuroinflammation in optic neuritis and suggest the potential of A2 blockade as a targeted therapy for MS-induced optic neuritis." (PMID 33735314, 2021).
pancreatic adenocarcinoma (1 paper, 2021). "Analysis of murine pancreatic adenocarcinoma (PDAC) tissue, which is associated with ARG2 and ASS1 upregulation, found a dramatic reduction in arginine levels in the interstitial fluid." (PMID 33979616, 2021).
Peptic ulcer (1 paper, 2013). The term peptic ulcer refers to acid peptic injury of the digestive tract, resulting in mucosal break reaching the submucosa. "Surprisingly, ARG2 was not apparently expressed in the stromal or epithelial cells surrounding necrotic tissue or myxoid degenerative areas in intraductal papillary-mucinous neoplasms of the pancreas and necrotic tissue in peptic ulcers (data not shown)." (PMID 23424623, 2013).
pneumonia (1 paper, 2025). An acute, acute and chronic, or chronic inflammation focally or diffusely affecting the lung parenchyma, caused by an infection in one or both of the lungs (by bacteria, viruses, fungi, or mycoplasma.). "The increased Arg2 expression in the PIS group compared to the pneumonia group within BM DEGs suggests that the systemic inflammatory response in sepsis enhances the release and peripheral migration of CXCR2Hi MDSCs, which might amplify ARG2-mediated immunosuppression." (PMID 40860137, 2025). "Consistent with the accumulation of CXCR2Hi MDSCs, ARG2 contents in blood samples from septic patients were significantly elevated compared to either the healthy (2.89 ng/mL vs. 0.65 ng/mL, p < 0.001) or the pneumonia (2.89 ng/mL vs. 1.67 ng/mL, p = 0.015) group." (PMID 40860137, 2025). "Notably, the CXCR2Hi MDSC, with higher ARG2 expression than the CXCR2Low subset, exhibited a pronounced increase in the sepsis group, as opposed to the healthy and pneumonia groups (0.85% vs. 0.23% and 0.01%, respectively, both p < 0.01)." (PMID 40860137, 2025).
prostate intraepithelial neoplasia (1 paper, 2010). A neoplastic proliferation of the epithelial cells that line the acini and the ducts of the prostate gland. "ARG2 was statistically significantly less expressed in tumor tissues compared to normal (p<0.001, Mann-U), to non-malignant normal adjacent (p<0.01, Mann-U) and to prostate intraepithelial neoplasia (PIN) tissues (p<0.001, Mann-U)." (PMID 20711410, 2010).
renal fibrosis (1 paper, 2020). A final common manifestation of a wide variety of chronic kidney diseases characterized by glomerulosclerosis and tubulointerstitial fibrosis. "The fact that pharmacologic blockade or genetic deficiency of Arg2 reduced renal fibrosis indicates that Arg2 is the primary target for arginase inhibition." (PMID 32956070, 2020). "Second, we showed that pharmacological blockade or genetic deficiency of Arg2 mediates renal tissue protection following renal fibrosis, as reflected by preservation of kidney interstitial fibrosis and fibrotic markers." (PMID 32956070, 2020). "Our findings, therefore, reveal an important role for Arg2 in the pathogenesis of renal fibrosis and provide evidence for arginase inhibition as a potential new therapeutic modality for treating patients with CKD." (PMID 32956070, 2020). "In conclusion, our study demonstrates for the first time to our knowledge that Arg2 plays an essential role in the development of renal fibrosis, mainly by targeting Arg2 expressed in endothelial cells." (PMID 32956070, 2020). "First, we showed increased Arg2 expression and arginase activity following renal fibrosis." (PMID 32956070, 2020). "Findings of our study may ultimately result in novel therapeutic interventions designed to attenuate arginase activity or signaling that regulates Arg2 expression in the treatment of renal fibrosis." (PMID 32956070, 2020). "Arg2 expression and arginase activity significantly increased following renal fibrosis." (PMID 32956070, 2020). "Our results, therefore could support a role for Arg2 in mitochondrial biogenesis following renal fibrosis." (PMID 32956070, 2020). "Our data show that selective deletion of Arg2 specifically in endothelial cells blunted the increase in renal fibrosis after UUO, indicating a possible direct role of endothelial cell Arg2 in the pathogenesis of renal fibrosis." (PMID 32956070, 2020). "In contrast, selective deletion of Arg2 specifically in proximal tubular cells (Ggt1Cre/Arg2fl/fl) failed to reduce renal fibrosis after UUO." (PMID 32956070, 2020). "Interestingly, deletion of Arg2 specifically in proximal tubular cells (Ggt1Cre/Arg2fl/fl) failed to reduce renal fibrosis and was similar to vehicle-treated UUO in Arg2fl/fl mice." (PMID 32956070, 2020).
retinal ischemia (1 paper, 2020). A ischemic disease that involves the retina. "Two isoforms of arginase enzymes (Arg-1 and, in a major proportion, Arg-2) are expressed in the retina, whose regulation could be crucial in the development of some retinopathies such as DR or retinal ischemia." (PMID 32961933, 2020).
retinopathy of prematurity (1 paper, 2023). A bilateral retinopathy characterized by neovascularization, scarring, retinal detachment, and eventually blindness. "Our laboratory has also shown that the expression of the mitochondrial isoform of arginase, arginase-2 (A2), increases early in mouse models of ONC injury as well as in models of ischemia/reperfusion injury (I/R) and retinopathy of prematurity (ROP)." (PMID 37816735, 2023).
sarcoma (1 paper, 2017). A usually aggressive malignant neoplasm of the soft tissue or bone. "Similar to the other sarcomas expression of ARG2 was highest, with modest expression of ARG1 and NOS2 genes." (PMID 28969007, 2017). "Gene set enrichment was carried out for all sarcoma and CNS tumour subtypes, using pre-ranked gene lists correlating with ARG2 and OTC." (PMID 28969007, 2017). "The analysis above indicates that the major paediatric sarcomas universally express SLC7A1, ARG2, and ASS, but have low OTC expression." (PMID 28969007, 2017).
Sepsis (1 paper, 2025). Sepsis is defined as life-threatening organ dysfunction caused by a dysregulated host response to infection. "This pattern of increased expression initially implicates a potential role for Arg2 in modulating T lymphocyte proliferation within the context of sepsis." (PMID 40860137, 2025). "The influence of ARG2 inhibition on CD4+ T cell functionality in vivo was further explored to delineate its role in sepsis immunopathology." (PMID 40860137, 2025).
small cell lung carcinoma (1 paper, 2011). Small cell lung cancer (SCLC) is a highly aggressive malignant neoplasm, accounting for 10-15% of lung cancer cases, characterized byrapid growth, and early metastasis. "As our data showed over expression of ARG2 in PCa, it is important to note that the protein is also altered in other cancer tissues such as small cell lung cancer where its expression is correlated with the dissemination of cancer cells." (PMID 21347291, 2011).
synovitis (1 paper, 2020). Inflammation of a synovial membrane. "In that study, they have demonstrated that Arg2 overexpression in mouse joint tissues causes OA with synovitis and loss of glycosaminoglycans in articular cartilage followed by upregulation of pro-inflammatory products, although, their data show ablation of Arg2 promoted IL-1β caused NO production." (PMID 31979015, 2020).
T cell deficiency (1 paper, 2025). "For instance, arginine depletion mediated by ARG2 is closely linked to T cell deficiency." (PMID 41219968, 2025).
thyroid cancer (1 paper, 2014). "These include C8orf4, also known as thyroid cancer 1 (TC-1), DUSP5, involved in ERK1/2 pathway attenuation, and ARG2, whose over-expression has been associated with the thyroid cancer pathogenesis." (PMID 24810336, 2014).
triple-negative breast carcinoma (1 paper, 2025). An invasive breast carcinoma which is negative for expression of estrogen receptor (ER), progesterone receptor (PR), and human epidermal growth factor receptor 2 (HER2). "In addition, knockdown of ARG2 in cultured triple-negative breast cancer cells markedly reduced cell growth." (PMID 40140975, 2025).
Ureteral obstruction (1 paper, 2020). Obstruction of the flow of urine through the ureter. "We hypothesized that endothelial arginase-2 (Arg2) promotes the development of kidney fibrosis induced by unilateral ureteral obstruction (UUO)." (PMID 32956070, 2020).
varicocele (1 paper, 2015). A condition characterized by the dilated tortuous veins of the spermatic cord with a marked left-sided predominance. "Our data shows the unique expression of ARG2 in varicocele men may be indicative of the poor sperm parameters seen in varicocele patients." (PMID 25890347, 2015). "ARG2 was uniquely expressed with low abundance in the unilateral varicocele group." (PMID 25890347, 2015). "Two proteins that were unique to the varicocele group were cysteine-rich secretory protein 2 precursor (CRISP2) and arginase-2, (ARG2)." (PMID 25890347, 2015). "Proteins expressed uniquely in the unilateral varicocele group were cysteine-rich secretory protein 2 precursor (CRISP2) and arginase-2 (ARG2)." (PMID 25890347, 2015).
tumor (115 papers, 2004 to 2026). "Specifically, tumor‐associated N2 neutrophils facilitate tumor growth and angiogenesis by secreting cytokines such as ARG2 and VEGF." (PMID 40530896, 2025). "CMV miRNA-613 decreases ARG2 and is associated with worse outcomes, including decreased survival and increased tumor size." (PMID 40563634, 2025). "Arg2 was also expressed in macrophages, albeit at low levels, and was the prevalent isoform in tumor-associated granulocytes." (PMID 36727849, 2023). "Another recent study using clinical samples showed that ARG2 was significantly upregulated in primary and recurrent tumor samples compared to normal tissues and associated with HCC progression." (PMID 38157378, 2023). "Strikingly, we also observed that the depletion of CD4+ T cells selectively improves tumor control in Arg2-deficient mice." (PMID 34037806, 2021). "Arginase enzymes facilitate localized immune suppression mediated by cancer-associated fibroblasts (ARG2), MDSCs, DCs, tumor-associated macrophages (TAMs) and tumor-infiltrating macrophages (ARG1)." (PMID 33747948, 2021). "Intense arginine uptake during the S/G2M phase noted in tumor cells leads to the release of ornithine, which has been associated with mitochondrial arginase 2 (Arg2) activity." (PMID 32488850, 2020). "ARG2 (Arginase 2) is a protein-coding gene, and an increase in its activity is usually associated with more advanced diseases and poor clinical prognosis, in addition to being closely related to tumor immune response 54-56." (PMID 34975331, 2022). "Furthermore, Arg2-deficiency in CD8+ T cells strongly synergized with PD-1 blockade for the control of tumor growth and animal survival." (PMID 34037806, 2021). "The unexpected association of high CAF-ARG2 expression with a low ARG2 expression by cancer cells suggests that in this quite common tumor phenotype, cancer cells may have developed an ‘exogenous-ARG independent’ metabolism." (PMID 34344457, 2021). "Moreover, cancer-associated fibroblasts and tumor-associated M2 macrophages from hypoxic regions overexpress ARG2 as well." (PMID 32872669, 2020). "Based on the observations that arginase inhibits T cell in the tumor microenvironment and thus promot cancer growth, novel immunotherapy vaccines targeting Arg1 or Arg2 have been developed and are now undergoing clinical trials." (PMID 39952693, 2025). "In arginine metabolism, PDAC cells promote tumor growth by catabolizing arginine into urea and ornithine through high expression of arginase 2 (Arginase 2)." (PMID 40356913, 2025). "Two isoforms of arginase, ARG1 and ARG2, are aberrantly expressed in various types of cancer and have been shown to play a crucial role in regulating tumor growth and metastasis." (PMID 41246357, 2025). "Arg2 also supports regulatory T cell function and survival, indicating its potential as a therapeutic target in autoimmune and neoplastic diseases." (PMID 39952693, 2025). "Overexpression of ARG2 by tumor cells can deplete arginine from the TME and contribute to T cell dysfunction as a result." (PMID 40563634, 2025). "While tumor cells increased expression of arginase 2 (Arg2), tumor-infiltrating myeloid cells (T-MCs) increased ArgI expression." (PMID 39763643, 2024). "These tumor types also showed high expression of arginase, particularly Arg2 as the major isoenzyme, suggesting their ability to transport and utilize arginine." (PMID 39239650, 2024). "In metastatic melanoma, Treg up-regulates the arginine catalytic enzyme arginase 2, increases the uptake capacity of Arg, promotes its proliferation capacity and recruitment to tumor tissues, and inhibits anti-tumor immunity." (PMID 39596288, 2024). "In particular, a reciprocal crosstalk between cancer and immune cells occurred regulating ARG2 expression in NB cells and favoring tumor development." (PMID 36980226, 2023).
tumor (continued). "Arginase 2, preferentially expressed in the kidneys, plays a significant role in the proliferation of tumour cells and the reduction in L-arginine availability." (PMID 38136342, 2023). "CCL2, ARG1, ARG2, NOS2, and CCL5 are well-known N2-associated cytokines that promote tumor growth, invasion, and immune suppression." (PMID 37174093, 2023). "In ccRCC, the repression of urea cycle enzymes, arginase 2 and argininosuccinate synthase 1, promotes tumor growth in part by conserving PLP." (PMID 37682999, 2023). "Reduced ARG2 activity promotes ccRCC tumour growth through at least two distinct mechanisms: preserving pyridoxal phosphate and preventing the accumulation of toxic polyamines." (PMID 38136342, 2023). "The regulation of ARG1 expression in MDSCs by IL-4, HIF-1α, and STAT3 is well established; however, the factors which regulate ARG2 in tumour cells have received less attention to date." (PMID 35962843, 2023). "In contrast, overexpression of Arg2 in B16F10 cells was able to rescue the decrease in tumor volume induced by sorafenib." (PMID 36604146, 2022). "CAFs also inhibit anti-tumor effector T cell responses through arginase II (ARG2), which converts arginine to ornithine, leading to a lack of arginine, as well as reduced lymphocyte infiltration and attenuated function." (PMID 35488263, 2022). "In the next step, we evaluated the activity of OATD-02 in the immunogenic Renca model, which is characterized by a strong infiltration of immunosuppressive Tregs and myeloid populations, as well as ARG2 expression by tumour cells." (PMID 36010962, 2022). "Arginase 2 is another enzyme for arginine metabolism, and knockout of arginase 2 in T cells can increase anti-tumor function in nutrient-unbalanced TME." (PMID 36231064, 2022). "Pharmacological inhibition of extracellular ARG1 has shown antitumour efficacy in various syngeneic tumour models, however, the importance of ARG2 as a therapeutic target has only been demonstrated by genetic deletion studies." (PMID 36010962, 2022). "qRT-PCR analysis of isolated tumor tissues from implanted mice showed that Arg2 mRNA expression was significantly inhibited, accompanied by a decrease in GPX4 level." (PMID 36604146, 2022). "Immunohistochemical analysis of tumor tissues showed that ARG2 is expressed in the cytoplasm of cancer cells and of cancer-associated fibroblasts (CAFs)." (PMID 34344457, 2021). "Depletion of arginine in the stroma by ARG2 expression by CAFs promote, eventually, an immunologically cold tumor phenotype that explains the poor prognosis of patients with ARG2 overexpression in the stroma." (PMID 34344457, 2021). "Overexpression, however, of ARG2 in the tumor stroma counteracts immune surveillance since, eventually, the tumor microenvironment becomes depleted from arginine as CAFs rapidly use the amino acid." (PMID 34344457, 2021). "Arg1 expression levels were significantly higher than Arg2 mRNA levels both in microglia and Mo/MΦ immunosorted from tumor-bearing brain." (PMID 34504786, 2021). "Reduced expression of key urea cycle enzymes including ASS1, ASL and ARG2 has been reported in a number of cancer types, suggesting tumor suppressive roles of these urea cycle enzymes." (PMID 34068137, 2021). "ARG2 is an enzyme that plays a part in the immunosuppressive tumor microenvironment and tumorigenesis." (PMID 33968341, 2021). "Reduced ARG2 levels promote tumor growth by two key mechanisms, i.e., conserving pyridoxal-5′-phosphate, a critical biosynthetic cofactor, and preventing a toxic buildup of polyamines." (PMID 34861885, 2021). "ARG2 suppresses tumor growth via depletion of biosynthetic cofactor PLP and toxic polyamine accumulation." (PMID 34068137, 2021). "ARG2 expression by cancer fibroblasts (CAFs) was a prevalent tumor feature as it concerned two-thirds of tumors." (PMID 34344457, 2021). "High expression of ARG1 and ARG2 was detected in malignant cells and tumor-infiltrating microglia/macrophages (MG/MΦ)." (PMID 34504786, 2021).